BDNF (brain derived neurotrophic factor)
Diseases named in the same sentence as BDNF in open-access papers (continued):
Sharing a sentence is not in itself a finding about the gene and the disease.
glioma (continued). "Within the framework of cancer neuroscience, research has illuminated that the secretion of BDNF and IGF‐1, coupled with direct synaptic interactions between glutamatergic and GABAergic neurons and OPCs, plays a crucial role in the malignant transformation of OPCs into glioma cells." (PMID 39469896, 2024). "We previously found that BDNF is one of multiple paracrine factors that can increase glioma proliferation in response to neuronal activity, albeit not as robustly as other neuron–glioma signalling mechanisms." (PMID 37914930, 2023). "Consistent with the hypothesis that BDNF functions to modulate synaptic strength through the CAMKII calcium signalling pathway, the CAMKII inhibitor KN-93 blocks the effect of BDNF on glioma glutamatergic current amplitude, whereas the inactive analogue KN-92 does not." (PMID 37914930, 2023). "The expression levels of BDNF, p-TrkB and ERK1/2 markedly decline after overexpression of TUSC7, whereas they are evidently raised after silencing TUSC7, suggesting that TUSC7 can suppress the proliferation and migration of glioma cells through inhibiting the BDNF/TrkB/ERK pathway." (PMID 37100464, 2023). "Furthermore, it has been reported that Rs4702-A is related to the increased expression of FURIN and brain-derived neurotrophic factor (BDNF) in the serum and peripheral blood mononuclear cells (PBMC) of glioma patients after radiotherapy, both of which are closely related to cognitive function." (PMID 36615706, 2022). "Apart from targeting the neuronal BDNF pathway, entrectinib gains importance in therapy and diagnostics of CNS tumors: The 2021 WHO classification identifies a new class of infant-type hemispheric glioma presenting with receptor tyrosine kinase fusions with ALK, ROS1, NTRK1/2/3, or MET." (PMID 36357661, 2022). "To explore the hypothesis that the growth-promoting effects of activity-regulated BDNF–TrkB signalling in glioma involves modulation of synaptic biology, we explored whether the effects of glioma TrkB signalling are related to or independent of AMPAR signalling." (PMID 37914930, 2023). "To further test whether BDNF–TrkB signalling regulates the number of neuron-to-glioma synaptic connections, we co-cultured glioma cells—with or without NTRK2 expression and expressing RFP-tagged PSD95—with neurons and quantified neuron-to-glioma synaptic puncta." (PMID 37914930, 2023). "BDNF expression levels in both non-treated and PROG-pre-treated glioma cells were similarly elevated by serotonin treatment with a concentration-dependent effect of serotonin on BDNF gene expression." (PMID 40141172, 2025).
metabolic syndrome (104 papers, 2010 to 2025). A cluster of metabolic risk factors for CARDIOVASCULAR DISEASES and TYPE 2 DIABETES MELLITUS. "In individuals with metabolic syndrome, the increase in BDNF levels after exercise has been shown to be associated with exercise benefits, including improvements in muscle strength, insulin resistance, and depressive symptoms." (PMID 40242707, 2025). "The lowest tertile of BDNF was associated with higher age, fewer cases of metabolic syndrome, lower levels of RBMT score, diastolic blood pressure, albumin, Hemoglobin A1c, low density lipoprotein, and estimated glomerular filtration rate." (PMID 33020545, 2020). "A recent meta-analysis found lower BDNF levels associated with the presence of metabolic syndrome in healthy adult subjects." (PMID 30542302, 2018). "Modifications of BDNF in plasma and/or in serum are associated with neurodegenerative and psychiatric disorders, cardiovascular diseases, metabolic syndrome and with mortality risk." (PMID 28914800, 2017). "Chronic elevated cortisol levels and leptin resistance can still explain the lower secretion of BDNF found in morbidly obese children and children with metabolic syndrome, and they are associated with deficits in cognition and synaptic plasticity." (PMID 27907172, 2016). "In this regard, studies reported decreased BDNF and synaptic loss in association with cognitive impairment and behavioral changes, in animal models of the metabolic syndrome." (PMID 23110484, 2012). "In summary, brain enzymatic markers of AA and DHA metabolism were increased in a rat model of early-stage metabolic syndrome, in association with reduced BDNF mRNA and protein, and drebrin mRNA." (PMID 23110484, 2012). "A significant decrease in plasma NGF and BDNF was associated with the metabolic syndrome and atherosclerosis." (PMID 20181009, 2010). "Plasma BDNF significantly correlates with multiple risk factors for metabolic syndrome and cardiovascular dysfunction." (PMID 20404913, 2010). "Plasma BDNF is associated with metabolic syndrome and cardiovascular risk." (PMID 40710520, 2025). "While human studies in this realm at this time focus primarily on risk factors associated with chronic health conditions including metabolic syndrome and inflammation, animal model studies show a link between IF and the improvement of cognitive performance via BDNF." (PMID 39798403, 2025). "Therefore, exercise that effectively stimulates sufficient BDNF secretion is preferable for individuals with metabolic syndrome or those who are overweight and at high risk of developing it." (PMID 40242707, 2025). "This suggests that reduced BDNF expression may contribute to developing peripheral organ diseases with metabolic syndrome as a possible proximate risk factor." (PMID 38672461, 2024). "In mice, global BDNF haploinsufficiency or brain-specific BDNF depletion results in excessive feeding and body weight gain accompanied by other features of the associated metabolic syndrome, including hyperleptinemia, hyperglycemia, and hyperinsulinemia." (PMID 30131705, 2018). "Therefore, we could raise a hypothesis that the loss of function of BDNF may be associated with metabolic syndrome and peripheral diseases." (PMID 38672461, 2024). "The effects of six weeks of moderate-intensity aerobic exercise supplemented with nano-curcumin on BDNF and inflammatory markers (IL-6 and IL-10) in patients with metabolic syndrome aged 60 to 65 years were also studied by Osali." (PMID 41228407, 2025). "Simultaneous use of nano-curcumin and aerobic exercise decreased serum MDA and hs-CRP levels while increasing BDNF, interleukin-10 (IL-10), and total antioxidant capacity in women with metabolic syndrome." (PMID 41228407, 2025). "Experiments on mice lacking the gene encoding BDNF have shown that exogenous administration of BDNF can reverse the effects of metabolic syndrome." (PMID 38152248, 2023).
metabolic syndrome (continued). "Genetic features, an unhealthy lifestyle, and stress disrupt BDNF signaling, possibly contributing to the pathogenesis of the metabolic syndrome." (PMID 37548699, 2023). "The aim of this study was to examine the serum BDNF concentrations in adolescents with metabolic syndrome and according to their body mass index (BMI) status." (PMID 37548699, 2023). "MVP study also pointed out that brain-derived neurotrophic factor (BDNF) downstream variants were linked with triglycerides and HDL levels and imply the association of this gene with T2D and metabolic syndrome." (PMID 35763080, 2022). "Leptin It is also found to be over-expressed in patients with metabolic syndrome synergistically with overexpression in BDNF and NGF- β." (PMID 36248655, 2022). "The protective role of IKKβ deficiency in astrocytes were reversed by BDNF inhibition, suggesting that the GABA-BDNF axis is important in regulating energy homeostasis and metabolic syndromes." (PMID 34957242, 2021). "Dyslipidemia and hypertension are major risk factors for coronary heart disease (CHD), and BDNF can play a regulatory role in blood pressure and lipid metabolism." (PMID 33343231, 2020). "The aim of this research was to investigate the effect of 6-week aerobic exercise with moderate intensity and consumption of nano-curcumin on IL-6, IL-10 and BDNF in 60–65 year females with metabolic syndrome (MS)." (PMID 32256716, 2020). "Aging, inflammation, oxidative stress, and metabolic syndrome are the main important factors in brain-derived neurotrophic factor (BDNF) level." (PMID 32256716, 2020). "This process leads to the memory potentiating effects of DHA and the induction of BDNF expression in the hippocampus of metabolic syndrome mice." (PMID 33343231, 2020). "Babaei P, Azali AK, Soltani TB, Damirchi A, Effect of six weeks of endurance exercise and following detraining on serum brain derived neurotrophic factor and memory performance in middle aged males with metabolic syndrome." (PMID 32876194, 2020). "In conclusion, Vit D insufficiency deteriorates metabolic syndrome components, and further supplementation significantly attenuates them parallel with reduction in BDNF." (PMID 29177013, 2017). "Vit D insufficiency deteriorates metabolic syndrome components, and elevates serum BDNF as a compensatory metabotropic factor, and further supplementation significantly attenuates these components parallel with reduction in BDNF." (PMID 29177013, 2017). "Chaldakov has previously found that circulating BDNF levels are decreased in subjects with advanced metabolic syndrome, whereas BDNF levels are elevated in subjects in the early stages of metabolic disturbances." (PMID 29028824, 2017). "Here, we studied the beneficial effects of aerobic exercise on metabolic syndrome components, cognitive performance, brain derived neurotrophic factor (BDNF) and irisin in ovariectomized rats with different serum vitamin D (Vit D) status." (PMID 29177013, 2017). "Retrieved papers revealed a larger amount of studies referring to the effects of exercise either on BDNF production, or on cognitive processing, in populations with metabolic syndromes, psychiatric disorders and some neurological diseases." (PMID 28469588, 2017). "In male samples alone, BDNF levels of patients with metabolic syndrome are 4.6 ± 4.7 ng/mL, whereas BDNF levels of patients without metabolic syndrome are 3.3 ± 3.8 ng/mL." (PMID 28562580, 2017). "In one study, plasma BDNF levels were positively correlated with several CVD risk factors and metabolic syndrome in white elderly subjects (mean age ~70 yrs)." (PMID 26161003, 2015). "In elderly participants in the Baltimore Longitudinal Study of Aging, BDNF was positively associated with several CVD risk factors including body mass index, diastolic blood pressure, and metabolic syndrome and these associations varied by sex." (PMID 26161003, 2015).
metabolic syndrome (continued). "Several previous investigators have found that type of diet could affect BDNF signaling in patients suffering from metabolic syndrome." (PMID 40255947, 2024). "Elevated NSE levels may reflect both neurologic impairment and metabolic syndrome, while reduced levels of BDNF were observed in patients with metabolic syndrome." (PMID 37047601, 2023). "Therefore, it can be concluded that a decrease in BDNF/Trk-B signaling in the liver is a crucial factor that contributes to the onset of metabolic syndrome symptoms." (PMID 38152248, 2023). "Furthermore, this nano-curcumin increased brain-derived neurotrophic factor and IL-10 levels, as well as antioxidant capacity, in the blood from subjects with metabolic syndrome." (PMID 36678282, 2023). "Indeed, by contributing to the regulation of both synaptic plasticity and energy metabolism, including feeding behavior, BDNF has been recognized as a key target in the relationship between metabolic syndrome and psychiatric diseases." (PMID 35911513, 2022). "These authors concluded that the higher IGF-I levels, might indicate disease progression, potentially as a compensatory response similar to the higher BDNF levels in metabolic syndrome." (PMID 35153701, 2021). "The inflammatory process can be a link between BDNF and dyslipidemia." (PMID 33343231, 2020). "Changes in blood BDNF levels and signaling may be a potential common factor for the metabolic syndrome and atherosclerosis playing a role in the development of cardiovascular disorders." (PMID 33343231, 2020). "In conclusion, training with or without the nano-curcumin supplementation and the supplementation alone could improve inflammation, BDNF concentration, and stress oxidative indices, as well as the glycemic level, in the elderly females with metabolic syndrome." (PMID 32256716, 2020). "Lately, the study of adiponectin and BDNF focuses on the finding of common therapy between metabolic disorders and CNS disease and emphasizes a greater understanding of the common regulatory mechanisms both in metabolic syndromes and brain dysfunction." (PMID 33375318, 2020). "The Met/Met genotype of the BDNF Val66Met polymorphism has a significant effect on BMI gain and metabolic syndrome in male but not female schizophrenic patients treated with long-term antipsychotic drugs." (PMID 32116676, 2019). "BDNF is located also in lungs, heart, spleen, gastrointestinal tract and liver, and it is involved in the development of cardiovascular and metabolic disorders, metabolic syndrome, and body weight gain." (PMID 30542302, 2018). "On the other hand, several lines of evidence support a hypothesis whereby neurotrophins, especially BDNF, play an essential role in with the initiation and development of both atherosclerosis and metabolic syndrome." (PMID 29997519, 2018). "Moreover, patients who meet the metabolic syndrome criteria and patients with acute coronary syndrome have significantly lower plasma BDNF levels." (PMID 30245717, 2018). "Thus, the objective of this study was co-treatment of Vit D supplementation with aerobic exercise on cognitive performance, metabolic syndrome components, serum BDNF and irisin level." (PMID 29177013, 2017). "Whole brain BDNF mRNA and protein levels were reduced in the high-sucrose group, in agreement with previous studies that showed reduced BDNF levels in animal models of the metabolic syndrome with behavioral impairment." (PMID 23110484, 2012). "Linear regression analysis revealed that plasma BDNF is associated with risk factors for cardiovascular disease and metabolic syndrome, regardless of age." (PMID 20404913, 2010). "Consequently, diet-induced dyslipidemia may be exacerbated by the downregulation of BDNF in heterozygotes individuals." (PMID 34580389, 2021).
metabolic syndrome (continued). "Furthermore, male BDNF Met/Met carriers with clozapine-induced metabolic syndrome exhibited significant higher fasting glucose levels than those with Val/Val or Val/Met genotypes; carriers of Met allele displayed elevated blood glucose and predicted lower memory scores." (PMID 28056856, 2017). "Injections of BDNF in the paraventricular nucleus (PVN) of obese rats fed HFD normalize energy intake, body weight, hyperlipidemia, hyperinsulinemia, and hyperleptinemia indicating that hypothalamic BDNF improves metabolic syndrome symptoms associated with insulin and leptin resistance." (PMID 28706476, 2017). "Researchers have found a link between BDNF and lipid metabolism, confirming previous findings that BDNF levels are strongly positively correlated with TC, TG, and LDL, which suggest that BDNF is involved in the management of dyslipidemia." (PMID 38397057, 2024). "In contrast to elite athletes, a higher level of serum BDNF was detected in subjects diagnosed with metabolic syndrome (MetS), which might reflect the compensatory role for BDNF." (PMID 35153701, 2021). "Administration of honey from Heterotrigona itama bees (1 g/kg body weight) in metabolic syndrome-induced rats decreased brain pro-inflammatory tumour necrosis factor-alpha (TNF-α) and increased brain-derived neurotrophic factor essential for memory and learning." (PMID 39980683, 2025). "In conclusion, the present report suggests that the ratio proBDNF/BDNF could help improve diagnosis and phenotyping of OAB in female patients in a context of metabolic syndrome." (PMID 37367881, 2023). "Sixteen articles were excluded by reading the full text: sixteen because they were not systematic reviews, one because it was not specific to BDNF, and another because it analyzed BDNF in patients with metabolic syndrome." (PMID 38137853, 2023). "It has been observed that those patients with chronic schizophrenia on long-term treatment with olanzapine and who suffer metabolic syndrome have lower scores in both immediate and delayed memory, attention, and total score in the RBANS battery, as well as lower levels of BDNF." (PMID 34220575, 2021). "In addition, the results of the present study suggested that nano-curcumin supplementation significantly increases serum concentrations of BDNF, IL-10, and TAC in subjects with metabolic syndrome." (PMID 32256716, 2020). "In addition, the results of the present study suggested that nano-curcumin supplementation significantly increases serum concentrations of BDNF, IL-10, and total antioxidant capacity (TAC) in subjects with metabolic syndrome." (PMID 32256716, 2020). "In contrast, in another study, subjects with or without metabolic syndrome had similar serum BDNF levels." (PMID 30542302, 2018). "BDNF levels of patients with metabolic syndrome are 3.7 ± 4.0 ng/mL, whereas BDNF levels of patients without metabolic syndrome are 3.4 ± 4.0 ng/mL." (PMID 28562580, 2017). "In female samples, BDNF levels of patients with and without metabolic syndrome are not statistically different (3.0 ± 3.5 vs 3.5 ± 4.3 ng/mL, P = 0.274)." (PMID 28562580, 2017). "Our results were in line with studies in Spanish and Taiwanese subjects, in that, BDNF concentrations did not correlate with MS and any metabolic syndrome component." (PMID 24444121, 2014). "Serum leptin levels were significantly higher in the metabolic-syndrome group than the control group (p < 0.01), but the BDNF difference between them was not significant." (PMID 24444121, 2014). "Like BDNF, GDNF signs in the suggested metabotropic hypothesis of metabolic syndrome." (PMID 35769087, 2022). "These pathways are physiologically related because cytokine-induced inflammation, if present in the metabolic syndrome, can alter the expression AA or DHA-selective PLA2’s and their downstream metabolites (e.g. eicosanoids) that modulate synapto-dendritic integrity and BDNF expression." (PMID 23110484, 2012).